BIN2 (bridging integrator 2)
Description:
Promotes cell motility and migration, probably via its interaction with the cell membrane and with podosome proteins that mediate interaction with the cytoskeleton. Modulates membrane curvature and mediates membrane tubulation. Plays a role in podosome formation. Inhibits phagocytosis.
Synonyms: BRAP-1
Tractability: Antibody: UniProt places it where antibodies can reach, with high confidence; its Gene Ontology location is reachable by antibodies, with high confidence; the Human Protein Atlas places it where antibodies can reach. PROTAC: ubiquitination databases record sites on it; its protein half-life has been measured.
Gene: Protein-coding gene on chromosome 12 (51,281,038 to 51,324,668, reverse strand). Ensembl gene ENSG00000110934.
Subcellular location: Cytoplasm; Cell projection, podosome membrane; Cytoplasm, cell cortex; Cell projection, phagocytic cup
Subcellular location (Human Protein Atlas): Plasma membrane
Pathways (Reactome):
Disease: Signaling by membrane-tethered fusions of PDGFRA or PDGFRB
Immune System: Neutrophil degranulation
Gene Ontology:
Molecular function: phospholipid binding; protein binding
Biological process: cell chemotaxis; phagocytosis, engulfment; plasma membrane tubulation; podosome assembly
Cellular component: cytoplasm; phagocytic cup; plasma membrane; podosome; extracellular region; ficolin-1-rich granule lumen; secretory granule lumen; cell cortex
Genetic constraint (gnomAD): Loss-of-function variants: 32 observed, 56.14 expected, observed/expected ratio (o/e) 0.57, 90% interval 0.43 to 0.77. The upper end of that interval is the gene's LOEUF score, 0.77, which puts it in group 3 of 6, group 1 being the genes least tolerant of losing a copy. Missense variants: 536 observed, 656.76 expected, observed/expected ratio (o/e) 0.82, 90% interval 0.76 to 0.88. Synonymous variants: 230 observed, 244.89 expected, observed/expected ratio (o/e) 0.94, 90% interval 0.84 to 1.05.
Homologues: Orthologues: chimpanzee BIN2 (98% identical), macaque BIN2 (93% identical), dog BIN2 (80% identical), pig BIN2 (73% identical), rabbit BIN2 (70% identical), mouse Bin2 (64% identical), rat Bin2 (64% identical), tropical clawed frog bin2 (41% identical), zebrafish bin2b (38% identical), zebrafish bin2a (29% identical), Drosophila melanogaster Amph (25% identical). Paralogues in human: BIN1 (35% identical), AMPH (31% identical), BIN3 (11% identical).
Diseases named in the same sentence as BIN2 in open-access papers:
BIN2 is named in the same sentence as 22 diseases in open-access papers, as found by Europe PMC text mining. Sharing a sentence is not in itself a finding about the gene and the disease. The quoted sentences say what the papers report.
endometriosis (3 papers, 2021 to 2023). The growth of functional endometrial tissue in anatomic sites outside the uterine body. "M1/M2 macrophage polarization is regulated by several genes (i.e., spleen tyrosine kinase, bridging integrator 2, metalloproteinase 12, chemokine receptor 5, macrophage mannose receptor 1, and TNF receptor type 1‐associated death domain) that are differentially expressed in endometriosis." (PMID 36310658, 2022). "qRT-PCR was carried out using the total RNA that was extracted from 10 pairs of normal endometrium and EM tissues and showed higher expressions of BIN2, CCR5, and MRC1 and lower expressions of SYK and ADAM12 in endometriosis tissue than in non-endometriosis tissue." (PMID 34295919, 2021).
atherosclerosis (2 papers, 2022 to 2023). A disease characterized by the build-up of fatty material and calcium deposition in the arterial wall resulting in partial or complete occlusion of the arterial lumen. "BIN2 regulates platelet activation in thrombosis, thrombo-inflammation, and atherosclerosis, and depletion of BIN2 is associated with protection from arterial thrombosis." (PMID 35203642, 2022).
ovarian carcinoma (2 papers, 2024). A malignant neoplasm originating from the surface ovarian epithelium. "Meanwhile the role of BIN2 in cancer remains yet unclear, TCGA studies have observed an association between upregulated BIN2 and favorable survival outcomes in all cervical, endometrial, breast, and ovarian cancers." (PMID 39108264, 2024).
Infertility (1 paper, 2021). "bin2-1 exhibited reduced fertility, aborted ovules, and short siliques similar to those of AIF2ox plants, and auxin partially rescued the infertility phenotype of bin2-1." (PMID 34386030, 2021).
ischemic stroke (1 paper, 2022). A stroke disorder caused by obstruction of blood flow to the brain, due to thrombotic (local blood clot formation) or embolic (due to a blood clot or other material traveling from another site) event. "Together, these results clearly pinpoint BIN2 as an important player in arterial GPVI-dependent thrombosis and ischemic stroke with subsequent brain infarction and tissue damage." (PMID 35203269, 2022).
leukemia (1 paper, 2012). A malignant (clonal) hematologic disorder, involving hematopoietic stem cells and characterized by the presence of primitive or atypical myeloid or lymphoid cells in the bone marrow and the blood. "Compared to human leukemia cells, mouse 8093 and Bin2 cells were significantly more sensitive to PHA-739358." (PMID 22721004, 2012).
male infertility (1 paper, 2024). The inability of the male to effect fertilization of an ovum after a specified period of unprotected intercourse. "Previous studies have reported that Arabidopsis BR deficient mutants exhibit inhibition in BR biosynthesis and signal transduction pathways, such as bin2 exhibiting reduced fertility or male infertility, and a significant decrease in pollen grain count." (PMID 39193214, 2024).
metabolic syndrome (1 paper, 2020). A cluster of metabolic risk factors for CARDIOVASCULAR DISEASES and TYPE 2 DIABETES MELLITUS. "Last, also the candidate regulators BIN2 and RAC2 have been associated with obesity and metabolic syndrome." (PMID 31688915, 2020).
metastatic melanoma (1 paper, 2025). A melanoma that has spread from its primary site to another anatomic site. "In addition, BIN2, CMTM8, CXCL10, HCLS1, ITGB2, PTPN2, and RFTN2 were expressed at significantly higher levels in our B16 brain-derived variants compared with the parent B16-F0 and are also upregulated in human metastatic melanomas compared with primary cutaneous tumors." (PMID 39819494, 2025).
myeloproliferative neoplasm (1 paper, 2017). A clonal hematopoietic stem cell disorder, characterized by proliferation in the bone marrow of one or more of the myeloid (i.e., granulocytic, erythroid, megakaryocytic, and mast cell) lineages. "Overexpressed BIN2 fusions were detected in myeloproliferative neoplasms." (PMID 28146432, 2017).
psoriasis (1 paper, 2025). An autoimmune condition characterized by red, well-delineated plaques with silvery scales that are usually on the extensor surfaces and scalp. "Additional Mendelian randomization analysis pinpointed seven marker genes linked to psoriasis: BIN2, CAPN12, CXXC5, KLRC1, KLRD1, PRF1, and SLFN5." (PMID 41328434, 2025). "By integrating single-cell RNA sequencing with MR analysis, we identified seven psoriasis-related genes (BIN2, CAPN12, CXXC5, KLRC1, KLRD1, PRF1, and SLFN5) that are highly expressed in CD4+ T cells." (PMID 41328434, 2025). "Thus, the identification of BIN2 in the context of psoriasis likely represents a novel finding in the current study, with no prior direct association in the literature." (PMID 41328434, 2025). "It has appeared as an upregulated gene associated with innate immune pathways in inflammatory skin conditions, but there are no reports of BIN2 being a psoriasis risk gene or a validated disease marker." (PMID 41328434, 2025). "BIN2 and CAPN12 are linked to an increased risk of psoriasis." (PMID 41328434, 2025). "The seven genes span established–emerging–novel tiers: PRF1 and KLRC1/KLRD1 are established in psoriasis immunity; SLFN5 is a recently reported systemic inflammatory marker; BIN2/CXXC5/CAPN12 lack prior links, suggesting novelty." (PMID 41328434, 2025). "Despite this role in innate immune function, BIN2 has not been prominently featured in past psoriasis research." (PMID 41328434, 2025). "KLRC1, KLRD1, PRF1, BIN2, and SLFN5 showed enrichment concentrated in immune-inflammatory modules—including IL-17 signaling, the TNF/NF-κB axis, and innate immune sensor pathways (NOD-, RIG-I-, and Toll-like receptors)—consistent with psoriasis-relevant Th17/innate activation." (PMID 41328434, 2025).
infection (3 papers, 2018 to 2025). The state of being infected such as from the introduction of a foreign agent such as serum, vaccine, antigenic substance or organism. "Previous studies indicated that BCTV C4 interacts with AtSKs and BIN2, interfering with BR signaling during infection." (PMID 29931348, 2018). "Transcriptomic analysis showed that phage narH, narG, and DNA methyltransferase genes were expressed, demonstrating that genes related to nitrate reduction and restriction-modification systems might be harnessed by phage Bin2 during the infection of MOB." (PMID 34479645, 2021). "The presence of RM-encoding genes may also result in a higher abundance of the phages Bin1 and Bin2 than phage Bin4, which share the same infection hosts as Bin1 and Bin2." (PMID 34479645, 2021). "In the recovered phage bins, we also identified genes related to bacterial defence systems, with 13 genes from Bin1, Bin2, and Bin3 being involved in RM, DISARM, bacteriophage exclusion system, abortive infection, Septu, or Zorya." (PMID 34479645, 2021).
tumor (3 papers, 2017 to 2023). "The results showed that elevated expression of TMC8 and BIN2 relative mRNA in tumor tissues compared to adjacent normal tissues." (PMID 32213661, 2020). "Results of tissue microarray IHC further certificated GBP1, BIN2 and LAP3 were overexpressed in EBVaGC tumour tissues." (PMID 36519208, 2023). "We also used data from Human Protein Profiles to demonstrate that the proteins encoded by seven immune-related genes were expressed at different degrees in HCC tissues, among which TMC8, BIN2, GIMAP7, and SPOCK2 were strongly to moderately positive in tumours." (PMID 32213661, 2020). "Furthermore, TMC8, BIN2 and SPOCK2 protein levels were also consistently higher expressed in tumor tissues than those in normal liver tissues." (PMID 32213661, 2020).
cancer (2 papers, 2017 to 2024). A tumor composed of atypical neoplastic, often pleomorphic cells that invade other tissues. "Differential expression and methylation of 3 selected candidates (BANK1, BIN2, and DTX1) were confirmed in an independent HNSCC cohorts from Johns Hopkins and TCGA (The Cancer Genome Atlas)." (PMID 28146432, 2017).
BIN2 also shares sentences with these, for which no sentence is quoted: breast carcinoma (2 papers); Arterial thrombosis (1); colorectal cancer (1); hepatoma (1); melanoma (1); Obesity (1); periodontitis (1); T-cell lymphoma (1).